EGFR (epidermal growth factor receptor)
Diseases named in the same sentence as EGFR in open-access papers (continued):
Sharing a sentence is not in itself a finding about the gene and the disease.
tumor (continued). "Targeted (ABY-029, anti-epidermal growth factor receptor (EGFR) affibody molecule) and untargeted (IRDye 680LT carboxylate) imaging agents were simultaneously injected 3-4 h prior to surgical tumor resection." (PMID 37427140, 2023). "In the same cases, the mean tumor staining intensity was 25 for VEGFR-2 (mean TBR 0.7), 7 for EGFR (mean TBR 0.9), 7 for IGF-1R (mean TBR 0.5), and 18 for CD40 (mean TBR 2)." (PMID 36979961, 2023). "Our data attributes decreased regional mean diffusivity (MD) in NE tumor regions to co-occurrence of EGFR amplification and CDKN2A homozygous deletion, which reflects a high tumor cell density in these regions." (PMID 37770427, 2023). "Elevated HIF-2α, for example, leads to the induction of EGFR and TGF-α contributing to cell proliferation and tumor growth." (PMID 36831657, 2023). "The epidermal growth factor receptor (EGFR), which is highly expressed in a variety of tumor types, has recently emerged as an ideal target for tumor identification." (PMID 37205904, 2023). "It reversibly binds to the ATP-binding site in the tyrosine kinase region of HER1 (EGFR) and HER2 cells, blocking downstream pathways, and thus inhibiting tumor growth." (PMID 37803271, 2023). "Sym004 has shown clinically meaningful rates of PR (13%) and minor tumor regression (44%) of target lesions in the Phase I trial (NCT01117428) in patients with KRAS WT mCRC and acquired resistance to anti-EGFR inhibitors." (PMID 38269272, 2023). "Increased expression of crucial proteins for angiogenesis, glucose metabolism, tumor growth and progression (VEGF, PDGF, EGFR, IGF, GLUT-1, CXCR, CAIX and XII), can contribute markedly to the tumorigenesis of RCC." (PMID 38273861, 2023). "Meanwhile, EGFR-TKIs can increase major MHC-I and -II molecules and induce T cell-mediated killing to tumor cells." (PMID 37345086, 2023). "In NSCLC, EREG reduces TKI-induced apoptosis through the EGFR/ERBB2 and AKT signaling pathways, thereby contributing to TKI resistance in tumor cells." (PMID 37091977, 2023). "Mechanistically, EMX1-FL bound to EGFR promoter, promoting EGFR transcription and activating EGFR-ERK signaling to trigger tumor metastasis." (PMID 38007497, 2023). "A multivalent structure comprised of an anti-EGFR VHH and two anti-HER2 affibodies coupled with Adriamycin, a chemotherapeutic drug, showed high anti-tumor activity both in vitro and in vivo." (PMID 37686035, 2023). "Similar to the EGFR gene, MEOX2 is localised on chromosome 7, and gains of chromosome 7 can, in part, explain its expression in a subset of tumours." (PMID 37568909, 2023). "Moreover, rebiopsy of tumor tissue demonstrated that EGFR-TKI administration was related to changes in the tumor microenvironment, resulting in a reduced proportion of anti-tumoral CD8+ and FOSP3+ tumor-infiltrating lymphocytes, increased PD-L1 expression, and tumor mutation burden." (PMID 36910653, 2023). "The EGFR plays a key role in the pathogenesis and progression of HNSCC, being overexpressed in more than 80% of patients both in the tumor and in the surrounding tissue." (PMID 37723219, 2023). "In the D5 (DAC stage), mTOR signaling (e.g., AKT2 and RPTOR) and EGFR signaling (e.g., EGFR and GSK3B) were overrepresented, implying the progression of cancer and tumor growth." (PMID 36991000, 2023). "EGFR and ESR1 are obtained from the intersection of tumor drivers and tumor targeting drug factors in the interaction network." (PMID 37542141, 2023). "Among patients with a right-sided primary tumor and wild-type RAS, anti-EGFR was the most frequently administered targeted therapy (>35% in all three treatment lines)." (PMID 37760572, 2023). "In addition, EGFR exon 20 insertions, Erb-B2 receptor tyrosine kinase 2 (ERBB2) mutations, neuregulin 1 (NRG1) fusions, KRAS proto-oncogene (KRAS) G12C, and tumor mutational burden (TMB) are evolving targeting/biomarkers and may eventually be included in the test panels, if possible." (PMID 37371816, 2023).
tumor (continued). "With regard to functional characteristics, CAFs produce growth factors such as epidermal growth factor (EGFR) and VEGF and also produce matrix metalloproteinases (MMPs), which are involved in the remodeling of the ECM and promote tumor growth and metastasis." (PMID 38003931, 2023). "Though first and second generation of EGFR TKIs (gefitinib, erlotinib, and afatinib) show favorable clinical outcome, up to 70% of patients eventually develop TKI resistance and tumor relapses upon 9 to 15 months of TKI treatment." (PMID 37495186, 2023). "This study attempted to determine the impacts of IL-17A on EGFR-mediated tumor proliferation and responses to EGFR-TKI treatment in LUAD, and to further investigate the mechanisms involved in the crosstalk between IL-17A and EGFR signaling." (PMID 37444399, 2023). "Anti-CD73 in combination with anti-PD-L1 therapy enhanced T cell response via upregulation of the number of CD8+ T cells and promotion of TNF-α and IFN-γ production in EGFR-mutant NSCLC, leading to inhibition of tumor growth." (PMID 36874015, 2023). "We evaluated the efficacy of Osimertinib in patients with EGFR mutant NSCLC and T790M in circulating tumour DNA (ctDNA)." (PMID 37894366, 2023). "It is possible that EGFR-TKI targeted therapy can effectively block the transmission of EGFR-related energy information, inhibit tumor cells from proliferating, and promote their apoptosis." (PMID 37250563, 2023). "A multi‐step sequence for CRC tumorigenesis has been proposed where alterations in genes involved in cellular pathways, such as EGFR (ERBB1/HER1), MAPK, PI3K, TGF‐β, and WNT/β‐catenin signaling pathways, occur at different stages of tumor progression." (PMID 37039257, 2023). "As a consequence, at this time mCRC patients will have a tumor that is composed of RAS WT cancer cells and is again potentially sensitivity to anti‐EGFR blockade." (PMID 36880426, 2023). "The combination of ethoxy-erianin phosphate and afatinib exerts synergistic effects on LIHC tumor growth and angiogenesis through VEGF/EGFR signaling." (PMID 37229243, 2023). "The Western blotting results showed that the expression of p-EGFR and PCNA (proliferating cell nuclear antigen) in the subcutaneous tumor tissues was significantly decreased in the acacetin group (50 mg/kg) compared with the control group (p < 0.05)." (PMID 37266143, 2023). "However, EGFR mutation was not predictive of overall survival or tumor control." (PMID 36676186, 2023). "We also validated the tumor suppressive roles of PLCD1 with multiple biological assays, which is achieved by suppressing Wnt/β-catenin and EGFR-FAK-ERK signaling in RCC cells." (PMID 36849889, 2023). "All four members of this family, including HER1 (EGFR, ErbB1), HER2 (Neu, ErbB2), HER3 (ErbB3), and HER4 (ErbB4), play an important role in cell growth regulation, proliferation, and tumor migration." (PMID 39355049, 2023). "Tumor markers (MUC1, EGFR, and EPCAM) are identified in CCA, and this marker combination is applied to detect tEVs in clinical bile samples." (PMID 36698298, 2023). "Afatinib, a TKI with an inhibitory effect on EGFR in addition to well as on HER2, was the most effective in suppressing tumor growth, with an IC50 of 0.35 μM." (PMID 36690964, 2023). "Our results support the notion that JMJD5 is a tumor suppressor in NSCLC through downregulating both WT and mutant EGFR, thereby inhibiting EGFR downstream signaling pathways and suppressing tumor growth." (PMID 37813845, 2023). "In an EGFR‐mutant NSCLC tumor xenograft mouse model, DS‐1205c in combination with gefitinib, erlotinib or osimertinib significantly delayed the onset of tumor resistance to TKIs compared with TKI monotherapy (Daiichi Sankyo, data on file)." (PMID 36621830, 2023). "Many tumor-specific genes and their transcripts were used as robust CTC markers (e.g., EGFR, CEA, and CKs)." (PMID 36835311, 2023).
tumor (continued). "In summary, 3DCRT combined with SBRT for patients with EGFR-mutant oligometastatic NSCLC has a better curative effect and is safer, and significantly improves the patient's immune and tumor marker levels." (PMID 36846051, 2023). "Patients from group B were newly found to have sensitizing EGFR mutations and gained access to EGFR-TKI therapy at recurrence; These patients had a PR rate of 50%, rPFS of 10 months, and rOS of 35.0 months, which appeared to be numerically inferior to group A and tumor heterogeneity may play a role." (PMID 37503313, 2023). "In many tumor types shallow deletion and low-level copy gain for CBX3 and RAC1, and in a lesser extend for EGFR, results in a proportional manner respectively significantly lower and higher mRNA levels of the corresponding genes." (PMID 37633946, 2023). "Next, we found that the levels of p-EGFR were inversely correlated with HDGF knockdown or overexpression in NSCLC cells and tumor tissues." (PMID 37301856, 2023). "The findings demonstrated that high levels of MMP11 in patients with EGFR-mutant LUAD are associated with a poor immune response and may control the tumor immune microenvironment, which fosters an immunosuppressive environment and aids in the immune escape of tumor cells." (PMID 36756152, 2023). "Proto-oncogenic signals primarily include tumor drivers HER2, EGFR, and the anti-apoptotic effector BCL-2." (PMID 36900322, 2023). "To date, various specific tumor markers, including HER2, PSA, EGFR (epidermal growth factor receptor), EpCAM, and MUC1 (mucin-1) have been used to isolate CTCs; among these, EpCAM has been extensively used." (PMID 37759483, 2023). "As a result, it aids in carcinogenesis and cancer metastasis by increasing cell survival and proliferation while lowering tumor cell death via regulating several client proteins, including HER-2, IGF-1R, ER, EGFR, and cytokine receptors." (PMID 36902446, 2023). "The selected targets were patient-specific, as the analysis of another individual’s HPV+ OPSCC, showed that although some interactions, such as VEGFA/NRP1 and VEGFA/GPC1 were present, the most active L-Rs in the tumor were VEGFA/NRP2 and EGFR-related pathways." (PMID 37704757, 2023). "In 4 patients who underwent biopsies after CAR-T cell treatment, there was a pathological eradication of EGFR-positive tumor cells, and CAR-EGFR genes were detected in TILs." (PMID 37646900, 2023). "Together, these results demonstrate the efficacy of the EGFR, Notch and PARP triple-targeting strategy for the treatment of NSCLC tumours, resulting in inhibition of bulk tumour cell growth and reduced tumorigenic cell frequency." (PMID 37441599, 2023). "BL-B01D1 is a bispecific ADC targeting EGFR and HER3, which induces cell cycle arrest in the S phase and subsequent apoptosis, leading to kill EGFR+ and/or HER3+ tumor cells." (PMID 38162667, 2023). "The regression of tumor cells was observed after a single intravenous injection of GCTO2 CAR-T cells, which is highly specific for EGFR vIII." (PMID 37190280, 2023). "In summary, targeting the EGFR/PI3K/AKT/mTOR signaling pathway via the inhibition of EGFR, PI3K, AKT, and/or mTOR has consistently shown anti-tumor effects on HCC cells in vitro." (PMID 37631344, 2023). "In the tumor microenvironment, autocrine and paracrine EREG activates the downstream pathways of EGFR to promote tumorigenesis." (PMID 37020674, 2023). "Pemigatinib treatment also caused the upregulation of microRNAs (miR-133b, miR-139, miR-186, miR-195) with tumor suppressor functions, along with the downregulation of validated protein targets with oncogenic roles (c-Myc, c-MET, CDK6, EGFR)." (PMID 37715207, 2023). "Another study showed that a conjugate of anti-EGFR VHH and hydrophilic PS IRDye700DX strongly binds to high EGFR expressing tumor cells and hardly bind to low EGFR expressing tumor cells, whereas PS IRDye700DX alone doesn’t bind to any cells." (PMID 37746282, 2023).
tumor (continued). "Epidermal growth factor receptor (EGFR), a member of the EGFR family, promotes tumor cell proliferation by activating downstream PI3K/AKT, MAPK, and JAK/STAT signaling pathways." (PMID 38162667, 2023). "Together, the EGFR and ERBB2 (HER2) gene expression data show that CTCs can be a valuable source of tumor information." (PMID 36900406, 2023). "The antitumor effect on target cells in vivo was further verified by EGFR CAR-T, EGFR CAR-E27-T, and EGFR CAR-E27-CCR6-T, and the tumor transplantation model of NSG mice was established." (PMID 36982500, 2023). "Similar strategies have been employed with an anti-EGFR and an anti-Her2 VHH conjugated with doxorubicin and showed good anti-tumor activity in vivo." (PMID 37686035, 2023). "It was demonstrated, for the first time, that the abundance of EGFR, INSR, VGFR3 and AXL, is lower in tumours relative to livers from healthy individuals whilst the opposite is true for IGF1R." (PMID 36890818, 2023). "further explored the mechanism of this observation and suggested that EGFR activation upregulates PD-L1 through p-ERK1/2p-c-Jun, leading to the apoptosis of tumor-infiltrating T cells." (PMID 36910653, 2023). "The role of AXL in EGFR inhibition resistance was established by analysis of AXL expression in tumor xenograft mice and in CRC patients after anti-EGFR treatment." (PMID 37469409, 2023). "FAK is a ubiquitously expressed nonreceptor tyrosine kinase that significantly contributes to the upregulation of growth factor receptors, such as EGFR and PDGFR, and it integrates signals governing oncogenesis and tumor progression in cancer cells." (PMID 37309001, 2023). "In sum, our data illustrated the strong association between EGFR genomic alterations and increased expression of ERK5 which could phosphorylate the PRPS1/2, activated nuclear biosynthesis pathway, and in turn might promote tumor cell proliferation and impact prognosis." (PMID 36720864, 2023). "NF‐κB also regulates TNF‐α and epidermal growth factor receptor (EGFR), forming a positive feedback regulatory loop between them to promote tumor cell proliferation." (PMID 37547175, 2023). "These domains encompass a diverse range of receptors that are specifically expressed in tumor cells (such as folate receptor (FR), human epidermal growth factor receptor-2 (HER-2), and epidermal growth factor receptor (EGFR)), as well as integrins." (PMID 38155903, 2023). "Neratinib is an oral, potent and irreversible third-generation EGFR TKI that inhibits tumor growth and metastasis by blocking the pan-HER family (HER1, HER2, and HER4) and downstream signaling pathway transduction." (PMID 37669923, 2023). "In clinical practice, when EGFR-TKI is used to treat NSCLC, the initial tumor shrinks rapidly, indicating that the drug concentration of EGFR-TKI is sufficient, and then there is a long-term SD persistent state." (PMID 37316870, 2023). "EBV T-cell activation only occurred when EGFR was expressed by HeLa-A2 cells, indicating that AEC binding to target positive tumor cells facilitates cleavage of EBV peptide and binding to HLA-A2 expressed by the tumor cells." (PMID 37261346, 2023). "The human epidermal growth factor receptor (EGFR) is closely related to several cancer-promoting processes and overexpressed on a variety of tumor types, rendering it an important target structure for the imaging and therapy of several malignancies." (PMID 37259420, 2023). "Overall, these findings demonstrated that PTPIP51 acts as a tumor suppressor in NSCLC, and its effects were mediated via PTEN activation and EGFR degradation." (PMID 37631304, 2023).
tumor (continued). "The present study corroborated that urolithins reduce the TME and inhibit tumor progression in GBM cells by regulating Akt and EGFR signaling pathways." (PMID 38068712, 2023). "This substantiates our finding that SUV, TPR and TBR show the same agreement with Patlak Ki values, indicating that the uptake of 89Zr-anti-EGFR and 89Zr-anti-HER3 in tumours is dominated by irreversible processes." (PMID 36820891, 2023). "Targeting the LLPS-mediated activation of EGFR and its downstream signaling pathways, such as MAPK, has emerged as a promising strategy for inhibiting tumor growth and metastasis." (PMID 37580790, 2023). "To corroborate these results in vivo, we subcutaneously injected control, LAMC2-KD, as well as LAMC2-KD + EGFR A549 cells into 4-week-old male BALB/c-nude mice, and evaluated real-time tumor progression using fluorescence imaging." (PMID 37542131, 2023). "Development of the model, incorporating patients’ clinical information such as tumor-lymph node-metastasis (TNM) staging and molecular biomarkers (ALK, EGFR, PD-1) will be followed and validated for large datasets that obtained from different institutions." (PMID 37081986, 2023). "In support of the oncogenic synergy between SRC and EGFR in PDAC, stable complexes between SRC and EGFR contribute to more aggressive tumor phenotypes by enhancing DNA synthesis and mitosis." (PMID 37120696, 2023). "Mice bearing combinations of E0771-EGFRvIII tumor cells and NIH 3T3 mouse fibroblasts in different ratios or E0771-EGFRvIII tumor alone were treated by EGFR-targeted CAR-T cells." (PMID 37046312, 2023). "HIPEC treatment restored the tumor suppression activity of the network comprising miR-145-5p and its target genes MYC, EGFR, MUC1, and OCT4." (PMID 37598177, 2023). "Vertically targeting the RAS signaling pathway by inhibiting EGFR and MEK led to a sustained PR in 47% of analysed tumour models and tumour growth control in more than 70%." (PMID 37604687, 2023). "The inhibitors target EGFR and HER2, blocking their signaling pathways and inhibiting tumor growth and progression." (PMID 37614311, 2023). "Further analysis of its pathological features revealed positive results for tumor‐related biomarkers, such as CA19‐9, CEA, EGFR, Ki67, and HER2." (PMID 37890865, 2023). "The ADC, made of the anti-EGFR cetuximab (Cet), used in CRC therapy, and ZA (Cet-ZA) can induce the proliferation of lymphocytes that become able to kill both tumor cells and TAF." (PMID 36765569, 2023). "Results showed that the protein levels of N-cadherin, Vimentin, Slug, p-HER2, p-EGFR, p-ERK1/2, MMP9 and MMP14 increased significantly in PLC/PRF-5LL−37 xenograft tumor; while significantly decreased in PLC/PRF-5LL−37 xenograft receiving si-LL-37 treatment." (PMID 36656313, 2023). "Of note, although JMT101 monotherapy showed minimal in vitro activity in EGFR 20ins, treatment with JMT101 in xenograft models led to a 60% tumor growth inhibition (P < 0.001)." (PMID 37308490, 2023). "Collectively, these in vivo data suggest potent and sustained anti-tumor activity of the combined therapy of KRASG12D and EGFR inhibitors." (PMID 37020035, 2023). "EGFR and HER2 expression on tumor cell lines was analysed before and after treatment of the cells with neuraminidase from Vibrio cholerae (NEU-VC) using the EGFR and HER2 directed antibodies cetuximab and trastuzumab, respectively." (PMID 37346044, 2023). "The addition of DCLK1 inhibitor DCLK1-IN-1 to the third-generation EGFR-TKI inhibitor Osimertinib resistant PDO downregulates the Wnt/β-catenin signaling pathway, restores tumor sensitivity to Osimertinib." (PMID 36696006, 2023). "In high-HER2-expressing BL0440 tumors and high-EGFR-expressing BL0269, inhibition of HRG1-ErbB3 binding reduced tumor volume." (PMID 37316561, 2023).